OTUD3 (OTU deubiquitinase 3)
Diseases named in the same sentence as OTUD3 in open-access papers (continued):
Sharing a sentence is not in itself a finding about the gene and the disease.
tumor (continued). "Targeting OTUD3 with rupatadine to simultaneously control DLBCL progression at both the tumor and T cell immune levels might be a promising choice, especially for elderly patients with limited tolerance." (PMID 39097608, 2024). "Our results confirmed that OTUD3 facilitated tumor growth by up-regulating YY1." (PMID 38351178, 2024). "The potential consequence of OTUD3’s downregulation of the mTORC1 pathway could be the suppression of tumor cell growth and proliferation." (PMID 38288086, 2023). "This series of results suggests that OTUD3 may play a role as a tumor suppressor gene in various cancers." (PMID 38288086, 2023). "Thus, OTUD3 downregulation was essential for nicotine-induced lymphatic metastasis, leading to earlier tumor relapse and shorter patient survival, especially in heavy smokers." (PMID 34853315, 2021). "Furthermore, we examined the relationship of OTUD3 levels with different clinicopathological characteristics and found that higher OTUD3 expression was correlated with larger tumor size, more vascular invasion, intrahepatic metastasis and worse TNM stage." (PMID 34380780, 2021). "Furthermore, our data showed that stable OTUD3 interference in HCCLM3 cells contributed to a decreased tumor volume and weight." (PMID 34380780, 2021). "OTUD3 stabilized the tumor-suppressive ZFP36 protein and induced rapid mRNA decay of VEGF-C." (PMID 34853315, 2021). "One possibility is that impairment of the OTUD3 function in SCCs, similarly to what was observed in breast carcinoma, may destabilize the tumor suppressor PTEN, thereby activating the AKT-mediated oncogenic signaling." (PMID 32560247, 2020). "Our experiment proved for the first time that OTUD3 is a tumor-suppressing DUB in BC." (PMID 32571254, 2020). "Targeting the OTUD3 upstream and downstream pathways may be a useful therapeutic strategy because BC cells may have lost the expression of such tumor-suppressing DUBs." (PMID 32571254, 2020). "As a tumor suppressor gene, OTUD3 may serve as a new biomarker of the occurrence and development of BC." (PMID 32571254, 2020). "However, in the tumor tissues with high miR-520h expression, OTUD3 and PTEN were expressed at low levels, and p-AKT was highly expressed." (PMID 32775453, 2020). "The deubiquitylase OTUD3 can function as a tumour-suppressor by stabilizing PTEN." (PMID 31266968, 2019). "Moreover, spontaneous tumor formation can scarcely be detected in OTUD3 KO mice within one year of age under normal feed conditions (data not shown)." (PMID 31266968, 2019). "Moreover, the tumor tissues from KrasG12D/WT/OTUD3 TG mice have faster cell proliferation, angiogenesis, and slower cell apoptosis rate as indicating with the Ki67, CD31, and cleaved Caspase-3 staining." (PMID 31266968, 2019). "To further validate the tumor promotion roles of OTUD3 in vivo, we evaluated the effect of OTUD3 on tumor growth in nude mice and found OTUD3 knockdown shrinked tumor growth whereas OTUD3 overexpression accelerated tumor growth in vivo." (PMID 31266968, 2019). "Additionally, we used NMR to examine the content levels of various metabolites between OTUD3-KO and wild-type HeLa cells, identifying several metabolites supporting the rapid growth and proliferation of tumor cells that were significantly elevated in OTUD3-KO cells." (PMID 38288086, 2023). "We also investigated whether OTUD3 knockdown would affect cell migration and tumor metastasis." (PMID 31266968, 2019). "Following analysis demonstrated that KrasG12D/WT/OTUD3 TG mice displayed more detectable nodules, larger tumor area, higher tumor grades than KrasG12D/WT/OTUD3 WT mice in the lung and exhibited poorer overall survival than those bearing tumors with normal expression level of OTUD3." (PMID 31266968, 2019).
tumor (continued). "Importantly, tumor sections from KrasG12D/WT/OTUD3 KO mice exhibited decreased cell proliferation, shrinked angiogenesis, and accumulated cell apoptosis signals than that of tumor tissues from KrasG12D/WT/OTUD3 WT mice, as indicated with the Ki67, CD31, and cleaved Caspase-3 staining." (PMID 31266968, 2019). "For instance, OTUB1 promoted NPC progression by regulating ferroptosis and radioresistance, while OTUD3 and OTUD4 impaired anti-tumor immune responses by stabilizing PD-L1 and CD73, respectively." (PMID 40469292, 2025). "In summary, OTUD3 modulates MYL12A stability, enhancing DLBCL survival and metastasis, and stabilizes PD-L1, promoting CD8+ T cell exhaustion and dampening tumor immunity." (PMID 39097608, 2024). "OTUD3, a deubiquitinase, stabilizes PTEN, suppressing tumor growth by inhibiting PI3K-AKT signaling." (PMID 38288086, 2023). "We find that OTUD3 is highly expressed in HCC tissues and that its expression is markedly correlated with tumor size, distant metastasis and TNM stage of HCC patients." (PMID 34380780, 2021). "We found that OTUD3 was significantly overexpressed in HCC, and higher OTUD3 expression was correlated with larger tumor size, more distant metastasis, and worse TNM stage." (PMID 34380780, 2021). "OTU domain-containing protein 3 (OTUD3) is recognized as a deubiquitinase of PTEN, thus acting as a tumor suppressor by stabilizing PTEN." (PMID 33066509, 2020). "Our findings demonstrated that OTUD3 is an essential regulator of PTEN and that the OTUD3-PTEN signaling axis plays a critical role in tumor suppression." (PMID 32775453, 2020). "Further research showed that significant correlations were observed between miR-520h/OTUD3/PTEN expression and histological grade, tumor size, and lymph node status." (PMID 32775453, 2020). "Here, we describe the functional characterization of a T. gondii deubiquitinase (TGGT1_258780) of the ovarian-tumor domain-containing (OTU) family, which, based on its structural homology to the human OTUD3 clade, has been designated TgOTUD3A." (PMID 27340699, 2016). "To determine whether OTUD3 promotes tumor progression by regulating YY1, we restored the expression of YY1 in endogenous OTUD3 depletion CRC cells or knocked down endogenous YY1 in OTUD3-overexpressing CRC cells." (PMID 38351178, 2024). "The OTUD3 and YY1 protein expression levels were positively correlated in the tumor samples." (PMID 38351178, 2024). "Moreover, by stabilizing different tumor drivers, OTU domain-containing protein 3 (OTUD3), USP22, and USP39 are also reported to determine the growth and progression of HCC." (PMID 35600879, 2022). "As a result, the OTUD3–PTEN axis represses cell migration and tumor metastasis significantly." (PMID 34575114, 2021). "OTUD3 was first identified as the deubiquitination enzyme of GRP78, mediating deubiquitination in tumor cells and maintaining the function of GRP78, so as to stabilize the proliferation of tumor cells." (PMID 32850882, 2020). "Compared with the negative control cells, the decreased OTUD3 protein levels increased the resistance of the tumor cells to cisplatin-induced apoptosis (p < 0.01)." (PMID 32571254, 2020). "The molecular bases of the putative tumor suppressor role of OTUD3 in SCCs have not been fully clarified." (PMID 32560247, 2020). "What is noteworthy is that OTUD3 promotes tumorigenesis both in tumor cells and in non-tumor cells within the microenvironment (for example, tumor stroma cell)." (PMID 31266968, 2019). "It has been reported that the deubiquitinating enzyme family OTUD3 can directly interact with the tumor suppressor protein PTEN and stabilize PTEN through deubiquitination modification, thereby antagonizing the PI3K-AKT signaling pathway and exerting a tumor suppressor function." (PMID 38288086, 2023).
tumor (continued). "To evaluate whether OTUD3 promotes tumor progression through regulating GRP78, we depleted endogenous GRP78 in OTUD3-overexpressing H1299 and A549 cells and observed that the inhibition of endogenous GRP78 expression attenuated OTUD3-induced cell growth and migration." (PMID 31266968, 2019). "However, the molecular basis of OTUD3 in SCC as a tumor suppressor has not been fully elucidated." (PMID 37829187, 2023).
cancer (16 papers, 2019 to 2025). A tumor composed of atypical neoplastic, often pleomorphic cells that invade other tissues. "Relevant evidence suggests that OTUD3 is strongly associated with the progression of several human cancers." (PMID 41050073, 2025). "Emerging evidence has suggested cancer-associated functions of OTUD3 in multiple types of human cancer." (PMID 36385557, 2022). "Undoubtedly, OTUD3 has consistently been linked to cancer progression and prognosis." (PMID 39097608, 2024). "Furthermore, researchers have observed in various databases that cancer patients with tumors of different locations and types exhibit one or more mutation sites with amino acid substitutions in the OTUD3 gene." (PMID 38288086, 2023). "By uncovering OTUD3’s essential role in cancer, this research provides crucial insights for developing novel cancer treatment strategies targeting OTUD3 or its regulatory pathways." (PMID 39048965, 2024). "Depletion of OTUD3 results in the activation of Akt signaling, inducing cellular transformation and facilitating cancer metastasis." (PMID 38288086, 2023). "To unravel the physiological roles of OTUD3 in multiple typical cancers, we crossed the OTUD3 KO and WT mice with MMTV-polyomavirus middle T antigen (PyMT) transgenic mice and KrasLSL-G12D/WT mice, separately." (PMID 31266968, 2019). "Moreover, OTUD3 depletion results in cell transformation, cancer metastasis induction, and AKT signaling pathway activation." (PMID 39144161, 2024). "OTUD3 plays a context-dependent role in diverse cancer types." (PMID 38539203, 2024). "It is speculated that OTUD3 function may be impaired in SCCs, destabilizing the tumor suppressor PTEN and thus activating the AKT pathway to cause cancer." (PMID 37829187, 2023). "OTUD3 appears to have both pro- and anti-cancer effects in cancer." (PMID 37829187, 2023). "OTUD3 plays context-dependent roles in tumorigenesis of different types of cancers." (PMID 37369659, 2023). "However, more clinical evidence and mechanistic studies are still needed to further elucidate the role of OTUD3 in cancer in order to target it for antitumor therapy." (PMID 37829187, 2023). "Compared with other DUBs, such as BAP1 and USP7, OTUD3 is rarely studied in cancer." (PMID 34380780, 2021). "OTUD3 was reported to play a context-dependent role in cancers." (PMID 34853315, 2021). "Notably, OTUD3 was downregulated in human cancers, contributing to enhanced cell proliferation, anti-apoptosis, and invasion." (PMID 34853315, 2021). "The genomic profiling of human cancers revealed that the Otud3 locus is targeted by gene deletion hits that may impair its function in multiple cancers, including HNSCCs, LSCCs and CESCCs." (PMID 32560247, 2020). "To further verify our findings, we tested whether OTUD3 can regulate GRP78 stability in other types of cancer cells." (PMID 31266968, 2019). "Similarly, upon genomic analysis of human cancers, OTUD3 locus deletion may be responsible for the development of multiple squamous cell carcinomas (SCCs)." (PMID 37829187, 2023). "Thus, OTUD3 is a potential drug target for anti-cancer therapy in NSCLC." (PMID 37369659, 2023). "However, an increasing number of investigations have emphasized the role of OTUD3 in cancer." (PMID 34380780, 2021). "In this review, we comprehensively summarize the roles of seven DUBs with OTU structural domains in cancer progression and antiviral immune responses, including OTUD1, OTUD2, OTUD3, OTUD4, OTUD5, OTUD6A, and OTUD6B." (PMID 41050073, 2025). "Thus, the OTUD3-PTEN axis could be a promising target for cancer prevention and treatment." (PMID 39144161, 2024).
cancer (continued). "Based on the analysis of combined GTEx (The Genotype-Tissue Expression project) and TCGA (The Cancer Genome Atlas Program) - DLBCL data, OTUD3 is highly expressed in cancerous tissues in contrast with healthy cells." (PMID 39097608, 2024). "HAUSP/USP7, USP10, USP11, USP13, OTUD3, and Ataxin-3 have all been recently identified as PTEN DUBs that control PTEN activity in different cancer-specific contexts." (PMID 36385557, 2022). "OTUD3 is the potent DUB for iron regulatory protein 2 (IRP2), implying the roles of OTUD3 in neurodegenerative disorders beyond multiple cancer pathogenesis." (PMID 35490179, 2022). "Conversely, OTUD3 interacts with and deubiquitylates GRP78, leading to its stability in cancer cells." (PMID 33585485, 2021). "Given the significance of USP10, USP11, USP13 and OTUD3 in PTEN stability, the development of a potent PTEN activation approach through manipulation of these DUBs may represent an attractive strategy for cancer prevention and treatment." (PMID 36385557, 2022). "OTUD3 expression in cancer tissues was independent of the molecular type and histological classification." (PMID 32571254, 2020). "Although not statistically significant, a trend indicating that OTUD3 may be downregulated in luminal B (Her-2-positive) cancer tissue compared with adjacent tissue was observed." (PMID 32571254, 2020).
iron metabolism disorders (3 papers, 2022 to 2026). "Considering that iron accumulates specifically in SN in the early stage of PD, we explored the influence of iron metabolism disorders caused by OTUD3 on neurons." (PMID 35490179, 2022).
animal diseases (1 paper, 2023). "In this paper, we first review the progress of research on the structure and molecular mechanisms and functions of OTUD3 in human and animal diseases and then describe the regulatory mechanisms of OTUD3 activity and expression." (PMID 37829187, 2023).
immune disorders (1 paper, 2025). "Elucidation of molecular mechanisms underlying such opposing effects on type I IFN responses by OTUD3 and OTUD5 and the identification of key molecules linked to both OTUDs may open up a new avenue for the development of novel treatments in patients with immune disorders including IBD." (PMID 41155222, 2025).
infection (1 paper, 2019). The state of being infected such as from the introduction of a foreign agent such as serum, vaccine, antigenic substance or organism. "Moreover, we imaged a separate cohort of KrasG12D/WT/OTUD3 WT and KrasG12D/WT/OTUD3 KO mice at 8 and 12 weeks post AAV-Cre infection using Micro-CT (Micro-Computed Tomography) imaging." (PMID 31266968, 2019).
malignant carcinoma (1 paper, 2021). "This study contributes to our ever-increasing understanding of the function of OTUD3 in malignant carcinoma and highlight the potential role of OTUD3 as a prognostic indicator and a therapeutic target in HCC." (PMID 34380780, 2021).
OTUD3 also shares sentences with these, for which no sentence is quoted: breast (1 paper); COVID-19 (1); dyslipidemia (1); inflammatory bowel disease (1); Insulin resistance (1); multiple myeloma (1); neurodegenerative disease (1); neurological disorders (1); nicotine addiction (1); ovarian carcinoma (1); ovarian serous cystadenocarcinoma (1); progressive multifocal leukoencephalopathy (1); retinopathy (1); severe acute respiratory syndrome (1); squamous cell carcinoma (1); steatosis (1); testicular germ cell tumor (1); thyroid cancer (1); uterine carcinosarcoma (1); uterine corpus endometrial carcinoma (1).